RB1 (RB transcriptional corepressor 1)
Description:
Tumor suppressor that is a key regulator of the G1/S transition of the cell cycle. The hypophosphorylated form binds transcription regulators of the E2F family, preventing transcription of E2F-responsive genes. Both physically blocks E2Fs transactivating domain and recruits chromatin-modifying enzymes that actively repress transcription. Cyclin and CDK-dependent phosphorylation of RB1 induces its dissociation from E2Fs, thereby activating transcription of E2F responsive genes and triggering entry into S phase. RB1 also promotes the G0-G1 transition upon phosphorylation and activation by CDK3/cyclin-C. Directly involved in heterochromatin formation by maintaining overall chromatin structure and, in particular, that of constitutive heterochromatin by stabilizing histone methylation. Recruits and targets histone methyltransferases SUV39H1, KMT5B and KMT5C, leading to epigenetic transcriptional repression. Controls histone H4 'Lys-20' trimethylation. Inhibits the intrinsic kinase activity of TAF1. Mediates transcriptional repression by SMARCA4/BRG1 by recruiting a histone deacetylase (HDAC) complex to the c-FOS promoter. In resting neurons, transcription of the c-FOS promoter is inhibited by BRG1-dependent recruitment of a phospho-RB1-HDAC1 repressor complex. Upon calcium influx, RB1 is dephosphorylated by calcineurin, which leads to release of the repressor complex (By similarity). (Microbial infection) In case of viral infections, interactions with SV40 large T antigen, HPV E7 protein or adenovirus E1A protein induce the disassembly of RB1-E2F1 complex thereby disrupting RB1's activity.
Synonyms: Rb; PPP1R130; OSRC; p105-Rb; p110-RB1; pRb; pp110
Tractability: Small molecule: a high-quality ligand is known; it has a binding pocket of medium quality; it belongs to a druggable protein family. PROTAC: ubiquitination databases record sites on it; its protein half-life has been measured; a small molecule that binds it is known.
Gene: Protein-coding gene on chromosome 13 (48,303,735 to 48,599,436, forward strand). Ensembl gene ENSG00000139687.
Subcellular location: Nucleus; Cytoplasm
Subcellular location (Human Protein Atlas): Nucleoplasm; Primary cilium transition zone
Pathways (Reactome):
Cell Cycle: APC/C:Cdh1 mediated degradation of Cdc20 and other APC/C:Cdh1 targeted proteins in late mitosis/early G1; Condensation of Prophase Chromosomes; Cyclin A:Cdk2-associated events at S phase entry; Cyclin D associated events in G1; Cyclin E associated events during G1/S transition; Inhibition of replication initiation of damaged DNA by RB1/E2F1; Phosphorylation of proteins involved in G1/S transition by active Cyclin E:Cdk2 complexes
Disease: Aberrant regulation of mitotic exit in cancer due to RB1 defects; Defective binding of RB1 mutants to E2F1,(E2F2, E2F3); Defective translocation of RB1 mutants to the nucleus; Nuclear events stimulated by ALK signaling in cancer; Replication of the SARS-CoV-1 genome; Replication of the SARS-CoV-2 genome
Cellular responses to stimuli: Formation of Senescence-Associated Heterochromatin Foci (SAHF); Oncogene Induced Senescence
Gene expression (Transcription): MLL4 and MLL3 complexes regulate expression of PPARG target genes in adipogenesis and hepatic steatosis; RUNX2 regulates osteoblast differentiation
Cell-Cell communication: Positive Regulation of CDH1 Gene Transcription
Gene Ontology:
Molecular function: disordered domain specific binding; DNA-binding transcription factor binding; identical protein binding; importin-alpha family protein binding; kinase binding; molecular adaptor activity; phosphoprotein binding; protein binding; ubiquitin protein ligase binding; RNA polymerase II transcription regulatory region sequence-specific DNA binding; transcription corepressor activity; enzyme binding; RNA polymerase II-specific DNA-binding transcription factor binding
Biological process: chromosome organization; heterochromatin formation; maintenance of mitotic sister chromatid cohesion; myoblast differentiation; negative regulation of DNA-templated transcription; negative regulation of gene expression; negative regulation of protein kinase activity; positive regulation of mitotic metaphase/anaphase transition; positive regulation of transcription regulatory region DNA binding; protein localization to chromosome, centromeric region; Ras protein signal transduction; regulation of DNA-templated transcription; regulation of lipid kinase activity; regulation of mitotic cell cycle; sister chromatid biorientation; aortic valve morphogenesis; cell morphogenesis involved in neuron differentiation; chromatin remodeling; negative regulation of apoptotic signaling pathway; negative regulation of cell cycle; negative regulation of cell growth; negative regulation of cold-induced thermogenesis; negative regulation of G1/S transition of mitotic cell cycle; negative regulation of inflammatory response; negative regulation of myofibroblast differentiation; and 12 more
Cellular component: chromatin lock complex; cyclin/CDK positive transcription elongation factor complex; nucleoplasm; nucleus; PML body; Rb-E2F complex; chromatin; cytoplasm; cytosol; SWI/SNF complex; spindle; transcription regulator complex
Genetic constraint (gnomAD): Loss-of-function variants: 16 observed, 101.47 expected, observed/expected ratio (o/e) 0.16, 90% interval 0.11 to 0.24. The upper end of that interval is the gene's LOEUF score, 0.24, which puts it in group 1 of 6, group 1 being the genes least tolerant of losing a copy. Missense variants: 761 observed, 957.58 expected, observed/expected ratio (o/e) 0.79, 90% interval 0.75 to 0.84. Synonymous variants: 317 observed, 328.67 expected, observed/expected ratio (o/e) 0.96, 90% interval 0.88 to 1.06.
Gene-disease validity (ClinGen):
ClinGen rates the evidence that RB1 causes each of these diseases.
retinoblastoma (autosomal dominant): Definitive. A malignant tumor that originates in the nuclear layer of the retina.
Cancer hallmarks: escaping programmed cell death (promotes); suppression of growth (promotes); genome instability and mutations (suppresses); invasion and metastasis (suppresses); change of cellular energetics (promotes); escaping programmed cell death (promotes or suppresses); escaping immune response to cancer (suppresses)
Homologues: Orthologues: chimpanzee RB1 (99% identical), macaque RB1 (99% identical), rabbit RB1 (94% identical), pig RB1 (94% identical), dog RB1 (93% identical), mouse Rb1 (91% identical), rat Rb1 (90% identical), guinea pig RB1 (86% identical), tropical clawed frog rb1 (59% identical), zebrafish rb1 (53% identical), Drosophila melanogaster Rbf (19% identical), Caenorhabditis elegans lin-35 (18% identical), and 1 more. Paralogues in human: RBL2 (28% identical), RBL1 (27% identical).
Diseases named in the same sentence as RB1 in open-access papers:
RB1 is named in the same sentence as 562 diseases in open-access papers, as found by Europe PMC text mining. Sharing a sentence is not in itself a finding about the gene and the disease. The quoted sentences say what the papers report.
retinoblastoma (575 papers, 1989 to 2026). "Parents of children with retinoblastoma can be categorised according to their likelihood of carrying a germline RB1 mutation." (PMID 42122192, 2026). "Retinoblastoma is the most common intraocular malignancy of childhood and is most often driven by loss of the RB1 tumor suppressor gene." (PMID 42187581, 2026). "Retinoblastoma (Rb) is an intraocular tumor caused by genetic alterations in the RB1 and MYCN genes within developing retinal cells." (PMID 41898516, 2026). "BACKGROUND: Retinoblastoma (Rb) is the most common childhood intraocular cancer, with heritable forms caused by pathogenic germline variants in the RB1 (or retinoblastoma 1) gene, which necessitate intensive and costly lifelong surveillance." (PMID 41764457, 2026). "Childhood eye tumors, such as retinoblastoma, are caused by biallelic inactivation of the retinoblastoma 1 (RB1) gene." (PMID 41210874, 2025). "Retinoblastoma is often initiated by a mutation in the RB1 gene, the first identified tumor‐suppressor gene." (PMID 40317918, 2025). "High-risk children are those with a known germline RB1 mutation or a positive family history of retinoblastoma, as they have an increased likelihood of developing the disease." (PMID 41002743, 2025). "Identifying RB1 mutations helps assess risks of new tumors, trilateral retinoblastoma, and secondary cancers." (PMID 41009976, 2025). "Retinoblastoma is a rare pediatric eye cancer caused by mutations in the RB1 gene, which regulates retinal cell growth." (PMID 40395327, 2025). "Children with germline RB1 mutations are at a significantly higher risk of developing retinoblastoma as well as secondary malignancies later in life." (PMID 40605078, 2025). "Our objective was to study the frequency of the different RB1 variants present in patients with retinoblastoma and correlate them with the functional domains of the pRb protein and with the clinical presentation." (PMID 41301786, 2025). "An additional challenge is that embryonal tumours have a low mutational burden and are driven by a few key genetic events (e.g., MYCN amplification in neuroblastoma, RB1 loss in retinoblastoma)." (PMID 41034452, 2025). "A mutation in the RB1 gene, the translated protein of which is a key regulator of the cell cycle, is the sole cause of inherited retinoblastoma." (PMID 39422807, 2025). "Genetic testing for RB1 pathogenic variants in the peripheral blood DNA is now a routine part of evaluating retinoblastoma patients." (PMID 41009976, 2025). "As expected, the vast majority of these pathogenic variants were identified in RB1, reaffirming its central and indispensable role in retinoblastoma pathogenesis." (PMID 41150792, 2025). "Retinoblastoma arises from mutations in the tumor suppressor gene RB1, also located on chromosome 13q14." (PMID 40926918, 2025). "Among these samples, the most common genetic variants involved the RB1 gene in 15/17 samples, 8 unilateral retinoblastoma samples and 7 bilateral retinoblastoma samples." (PMID 40332023, 2025). "Retinoblastoma has a strong genetic component and is often initiated by biallelic mutations in the RB1 gene, which is located on chromosome 13q14.2 and has 27 exons." (PMID 41009976, 2025). "Here, we present a comprehensive analysis of RB1 germline mutations in a cohort of 167 Rb patients between the years 2017 and 2023." (PMID 40317918, 2025). "A majority of patients with heritable retinoblastoma are heterozygous for RB1 alleles that create a premature termination codon." (PMID 41009976, 2025). "Biallelic loss‐of‐function mutations in the tumor suppressor gene RB1, situated on the chromosomal region 13q14, are responsible for initiating retinoblastoma in 95% of cases." (PMID 40317918, 2025).
retinoblastoma (continued). "PB incidence increases in children with bilateral retinoblastoma due to a germline mutation in the RB1 tumor suppressor, a condition referred to as ‘trilateral retinoblastoma’." (PMID 40075567, 2025). "Mutations in the RB1 gene are the sole cause of inherited retinoblastoma, and the protein it encodes is a key regulator of the cell cycle." (PMID 41174671, 2025). "The constitutional loss of one RB1 allele predisposes individuals to cancer, and the loss of the other allele in a developing retinal cell triggers the formation of retinoblastoma tumors." (PMID 40317918, 2025). "Such categories include, e.g., the Wilms tumors, in which LOI of IGF2 is a common early initiating event, or the childhood onset retinoblastoma, in which biallelic loss of RB1 is an early causal event." (PMID 40414875, 2025). "In this study, we aimed to identify RB1 mutations in retinoblastoma patients using Sanger sequencing, supplemented by multiplex ligation‐dependent probe amplification (MLPA) for some patients." (PMID 40317918, 2025). "Identifying a mutation in the RB1 gene in the affected patient (proband) is crucial in assessing the genetic risk of heritable retinoblastoma." (PMID 41009976, 2025). "Retinoma is a benign precursor of retinoblastoma that involves disruption of both alleles of the RB1 gene." (PMID 39755235, 2025). "In this study, we aim to identify RB1 mutations in retinoblastoma patients using Sanger sequencing in combination with multiplex ligation‐dependent probe amplification (MLPA)." (PMID 40317918, 2025). "Genotype-phenotype correlation studies of retinoblastoma suggested missense or splice variants of RB1 are related to incomplete penetrance, conforming to the unilateral manifestation of the disease in this patient." (PMID 40702147, 2025). "He observed that inheriting a mutation in only one copy of the RB1 gene predisposed individuals to develop a retinoblastoma when there was a second mutation in the other allele." (PMID 40227591, 2025). "Aqueous humor (AH) is an important source of tumor-derived genetic material, underscoring its potential use in liquid biopsies for retinoblastoma, particularly for detecting mutations in the RB1 gene, as recently demonstrated." (PMID 40332023, 2025). "As noted, some patients with familial retinoblastoma, which carry RB1-germline mutation, develop both retinoblastoma, an ocular tumor, and PB, a condition termed “trilateral retinoblastoma”." (PMID 40075567, 2025). "The prevalent location of RB1 variants in the Pocket domain correlates with the high pathogenicity of variants occurring in retinoblastoma." (PMID 41301786, 2025). "On a mechanistic level, elevated DNMT expression and increased global DNA methylation in peripheral blood and tumor tissue suggest a co-oncogenic role of methylation in retinoblastoma beyond RB1 mutations." (PMID 41150792, 2025). "(Background) Retinoblastoma is the most common intraocular malignancy in childhood, primarily caused by mutations in the RB1 gene." (PMID 41150792, 2025). "The general frequency of germinal RB1 gene mutation in patients with retinoblastoma is approximately 35%." (PMID 40317918, 2025). "By screening embryos for the RB1 gene mutation linked to retinoblastoma, parents can prevent passing on the genetic propensity to their children." (PMID 41009976, 2025). "First, the presence of germline RB1 mutations in a subset of PB in context of trilateral retinoblastomas indicated a role of this tumor suppressor gene." (PMID 41291966, 2025). "In bilateral retinoblastoma, a germline RB1 mutation is found in ~95% of cases using peripheral blood DNA alone." (PMID 41009976, 2025). "Although retinoblastoma is predominantly a monogenic condition associated with the RB1 gene, differences in laterality (unilateral versus bilateral) markedly affect the occurrence of harmful mutations." (PMID 41009976, 2025).
retinoblastoma (continued). "The detection of RB1 mutations in peripheral blood indicates germline disease, substantially elevating the risk of bilateral retinoblastoma development." (PMID 40001157, 2025). "Approximately one‐third of children diagnosed with retinoblastoma are associated with germline mutations in one of the RB1 alleles." (PMID 40317918, 2025). "Early AH sampling is therefore likely to be important in maximising cfDNA concentration and the subsequent detection of somatic RB1 pathogenic variants in retinoblastoma patients undergoing conservative treatment." (PMID 38672657, 2024). "Heterozygous pathogenic variants in RB1 in constitutional DNA represents not only a risk factor for the development of retinoblastoma but also other subsequent primary malignancies (SPM) particularly soft tissue sarcoma and osteosarcoma." (PMID 38240863, 2024). "Such profile is consistent with an origin of the tumour in the cone progenitor lineage and is similar to the cell-of-origin for RB1-deficient retinoblastomas." (PMID 37606819, 2024). "The present study firstly reports a novel gross deletion variant of the RB1 gene coexisting with two pathogenic CNVs in a pediatric patient with retinoblastoma and comorbid global developmental delay in China." (PMID 39108315, 2024). "Retinoblastoma (RB) is the most common intraocular malignant tumor in children, primarily attributed to the bi-allelic loss of the RB1 gene in the developing retina." (PMID 38920989, 2024). "Types of pathologic RB1 gene mutations detected in 14 out of 50 children with unilateral retinoblastoma, and correlation with tumor stage and eye salvage." (PMID 39234041, 2024). "Mutations in the RB1 gene or alterations in the Rb protein can disrupt cell cycle control, as evident in retinoblastoma and osteosarcoma." (PMID 38983782, 2024). "Among all patients with unilateral Rb in this cohort, 28% were found to have germline RB1 mutations." (PMID 39234041, 2024). "Within this study we have assessed RB1 pathogenic variant detection in an extended cohort of 75 aqueous humour samples from 68 retinoblastoma patients." (PMID 38672657, 2024). "The Retinoblastoma Susceptibility gene (RB1) was the initial human tumor suppressor gene to be discovered, and it plays a crucial role in the formation of retinoblastoma, a type of cancer that affects children’s eyes." (PMID 38966421, 2024). "Up to 80% of all heritable retinoblastoma cases can be attributed to de novo germline mutations in the RB1 gene." (PMID 38893137, 2024). "The clear-cut origin of retinoblastoma has not yet been determined; however, based on experiments, it has been suggested that RB1 loss in cone photoreceptors causes retinoblastoma." (PMID 38398694, 2024). "Loss of function of the retinoblastoma gene (RB1) is a key step in initiating both hereditary and sporadic forms of retinoblastoma tumors." (PMID 39000021, 2024). "They further demonstrated that LY3295668 has the potential to induce cell mitotic defects and cell apoptosis, as evidenced by its efficacy in an in vivo xenograft mouse model with RB1-deficient retinoblastoma." (PMID 38672640, 2024). "Over 99% of retinoblastomas are due to the loss of function of the RB1 tumour suppressor gene, caused by single nucleotide variants (SNVs), copy number variants (CNVs), loss of heterozygosity (LOH), or hypermethylation of the promoter." (PMID 38672657, 2024). "Biallelic loss-of-function mutations in the tumor suppressor gene RB1, located on chromosomal region 13q14, account for the initiation of retinoblastoma in 95% of cases." (PMID 38398694, 2024). "Retinoblastoma, a childhood cancer, is most frequently caused by bi-allelic inactivation of RB1 gene." (PMID 37606819, 2024). "Patient #4 was an 11-year-old male with a known germline RB1 mutation and a history of metastatic retinoblastoma who developed grade 3 osteoblastic osteosarcoma of the right proximal tibia with numerous bilateral lung metastases." (PMID 39590147, 2024).